TIMP1 (TIMP metallopeptidase inhibitor 1)
Diseases named in the same sentence as TIMP1 in open-access papers (continued):
Sharing a sentence is not in itself a finding about the gene and the disease.
cognitive decline (6 papers, 2020 to 2024). "TIMP-1 was shown to improve Aβ-induced cognitive decline by restoring the PI3K/Akt signaling pathway and maintaining synaptic function." (PMID 38891891, 2024). "Administration of ulinastatin before general anaesthesia mitigated cognitive decline in rats with POCD, likely through the prevention of BBB dysfunction, as evidenced by the lower BBB permeability and increased TIMP-1 expression." (PMID 39684217, 2024). "Furthermore, the mechanisms by which MMP-9 and TIMP-1 influence neurodegeneration, the reduction in hippocampal volume, and cognitive decline are not yet fully elucidated." (PMID 38891891, 2024).
coinfection (6 papers, 2014 to 2022). The simultaneous infection of a host by multiple pathogen species. "Despite these limitations, we have demonstrated that HIV and HCV mono-infection and co-infection increase the level of EPM, which might induce the expression of profibrogenic genes, such as TIMP1, via the ERK signaling pathway and subsequently increase the proliferation and invasion of HSCs." (PMID 27362846, 2016).
colorectal tumor (6 papers, 2001 to 2024). "Although TIMP‐1 expression is up‐regulated in colorectal tumor tissue, the molecular mechanisms underlying the prognostic effect of TIMP‐1 in CRC remain unclear." (PMID 31545548, 2019). "With the help of the HPA database, we identified that TIMP1 has a high expression in colorectal tumor tissue." (PMID 36146640, 2022). "From a clinical perspective, TIMP-1 is correlated with poor prognosis in several cancers including breast and colorectal tumors, as well as lymphoma and non-small cell carcinoma of the lung." (PMID 22957045, 2012). "Studies have correlated high TIMP-1 with breast and colorectal tumor resistance to hormone therapy, cyclophosphamide/methotrexate/5-fluorouracil, cyclophosphamide/epirubicin/5-fluorouracil, cyclophosphamide/adriamycin/5- fluorouracil, or single agent adriamycin." (PMID 22957045, 2012). "There was no increase in mRNA for MMP-9 or its specific inhibitor TIMP-1 in colorectal tumour tissue compared to normal, MMP-9 protein localized to the inflammatory infiltrate." (PMID 11401321, 2001).
depression (6 papers, 2013 to 2024). "Dysregulation of TIMP1 expression is hypothesized to be a basis for abnormal cognitive abilities, and its upregulation may be responsible for the development of major depressive disorder." (PMID 37628746, 2023). "Because severe skull fracture was observed together with skull depression and bleeding, the high TIMP-1 gene expression in the brain was probably a rapid and acute response to the massive infiltration of proinflammatory cytokines that occurred in the brain after dural injury and bleeding." (PMID 31441378, 2020).
dilated cardiomyopathy (6 papers, 2012 to 2025). Cardiomyopathy which is characterized by dilation and contractile dysfunction of the left and right ventricles. "Both TIMP1 and MMPs are increased in the myocardium in dilated cardiomyopathy; however, more information is needed." (PMID 34449561, 2021). "In addition, MMP9 tissue inhibitor metalloproteinase (TIMP-1) ratio was increased 3–5 times in patients with dilated cardiomyopathy." (PMID 34685620, 2021). "Similarly, in a mouse model of chronic myocarditis and dilated cardiomyopathy induced by coxsackievirus B3 (CVB3), the study found increased levels of Th22 and IL-22, along with upregulation of MMP-9 expression and downregulation of metalloproteinase inhibitor-1 (TIMP-1) expression." (PMID 38879568, 2024).
endometrial cancer (6 papers, 2010 to 2024). Primary or metastatic malignant neoplasm involving the endometrium (mucous membrane that lines the endometrial cavity). "High serum TIMP-1 levels have been associated with adverse prognoses in patients with endometrial carcinoma." (PMID 25036034, 2014). "The serum levels of HA and the SHAP-HA complex had a significant correlation with the MMP-9, and TIMP-1 in endometrial cancer patients." (PMID 21904555, 2011). "Former studies showed an involvement of Sdc-1 in MMP-9 regulation, a main target of TIMP-1, mediating endometrial cancer invasion." (PMID 21044331, 2010). "The SHAP-HA complex may promote the lymph-vascular space involvement and the synthesis and activation of MMP-9 and TIMP-1 in the progression of endometrial cancer." (PMID 21904555, 2011). "The present study has also demonstrated that the serum levels of MMP-9 and TIMP-1 were significantly higher in the endometrial cancer group than in the healthy control group, and serum MMP-9 was elevated according to the depth of myometrial invasion and lymph-vascular space involvement." (PMID 21904555, 2011). "Because the levels of the SHAP-HA complex showed a significant positive correlation with the levels of MMP-9 and TIMP-1, the SHAP-HA complex may promote the lymph-vascular space involvement and the synthesis and activation of MMP-9 and TIMP-1 in the progression of endometrial cancer." (PMID 21904555, 2011).
gastric adenocarcinoma (6 papers, 2017 to 2026). "Although serum CK18, MMP-9, and TIMP1 preop measurements in patients scheduled for curative surgery due to gastric adenocarcinoma did not help to gain any idea of tumor resectability, we concluded that our study had valuable results in significantly predicting N3 stage." (PMID 29651326, 2018).
glomerulosclerosis (6 papers, 2012 to 2025). A hardening of the kidney glomerulus caused by scarring of the blood vessels. "On the other hand, increased TIMP-1 and -2 expression in glomeruli was found in patients with glomerulosclerosis, and elevated urine concentrations of TIMP-1 in CKD patients correlated with those of tenascin, an ECM glycoprotein." (PMID 27455234, 2016). "In addition, both TIMP1 and TIMP2 are associated with glomerulosclerosis." (PMID 35045102, 2022). "The expression of TIMP-1 was downregulated, while the mRNA and protein expression and activities of MMP-2 and MMP-9 were enhanced after treatment with benazapril and all-trans retinoic acid (ATRA) in Wistar rat model of glomerular sclerosis compared to normal group." (PMID 23057632, 2012).
nasal polyp (6 papers, 2014 to 2021). "MMP-9, which mainly degrades gelatin, aggrecan, and elastin, was considered to be associated with nasal polyp formation and TIMP-1 regulated MMP-9 activity." (PMID 33477617, 2021). "Another study on the relationship between MMP and cytokines in nasal polyps reported a significant correlation between IL-5 and TIMP-1, suggesting their potential role in the maintenance of homeostasis in nasal polyp." (PMID 33477617, 2021). "When the nasal polyp fibroblasts were stimulated with Alternaria TIMP-1 mRNA and protein expressions were significantly increased." (PMID 29076987, 2017). "The MMP-9 level was elevated in nasal polyps and the TIMP-1 level was elevated in chronic rhinosinusitis." (PMID 29076987, 2017). "Findings of increased concentrations of MMP-9, but not of TIMP-1, in nasal polyps suggest that the MMP-9/TIMP-1 imbalance is associated with ECM degradation in CRSwNP." (PMID 25379119, 2014). "In an experimental study using organ culture of nasal polyps, S. aureus infection promoted the release of MMP-2, MMP-9, TIMP-1, and Th2 cytokines, including IL-5, IL-13, and eotaxin." (PMID 33477617, 2021). "However, another study revealed that the increased levels of MMP-2 in nasal polyps elevated MMP-9 expression in CRSsNP, and decreased levels of TIMP-1 in both CRSsNP and CRSwNP were comparable to those in the controls." (PMID 33477617, 2021).
ovarian tumors (6 papers, 2009 to 2021). "In summary, to the authors’ knowledge, our report is the first to evaluate the diagnostic usefulness of MMP-7 and TIMP-1 independently and, especially, in combination with both established ovarian tumor markers." (PMID 28662671, 2017). "The strength of this study is immunohistochemistry-based localization of TIMP-1, -2 and -3 coinciding with the expression of CA-125 on the same ovarian tumor sections, showing positive localization of TIMPs in the actual tumor cells." (PMID 35047406, 2021). "This particular study noted enhanced mRNA expression of TIMP-1 in high-grade ovarian tumors obtained from KM-plotter database." (PMID 35047406, 2021). "The very high level of TIMP-1 in ascites compared with blood plasma indicates the intensive secretion of TIMP-1 into the peritoneal cavity and its role in the ovarian tumor microenvironment." (PMID 34572929, 2021). "Contrary to the immunohistochemistry expression of TIMP-1 in ovarian tumors, the concentration of TIMP-1, measured by ELISA, was much higher than the concentrations of TIMP-2 and TIMP-3 (***p>0.0001 vs TIMP-3; *p>0.05 vs TIMP-2) in the ascites of CN patients." (PMID 35047406, 2021). "Immunohistochemistry staining of TIMP-1, -2 and -3 was performed on 36 benign and ovarian tumor samples." (PMID 35047406, 2021). "We observed higher SE ranges of MMP-7 and tumor markers in more advanced ovarian tumor stages (exception – TIMP-1)." (PMID 28662671, 2017). "Timp1 levels were elevated more than 400-fold and 250-fold in ovarian tumor fluid and peritoneal ascites compared to murine plasma, respectively." (PMID 19936259, 2009). "In addition, there was a significantly higher intracellular mRNA expression of TIMP-1, -2 and -3 in CN ascites-epithelial or tumorigenic cells compared to either benign or primary ovarian tumors." (PMID 35047406, 2021). "However, we show low expression of TIMP-1 in ovarian tumors compared to the expression of TIMP-2 and -3." (PMID 35047406, 2021). "Our results also demonstrated that TIMP1 is present in CTCs from patients with ovarian tumors." (PMID 32423054, 2020). "However, TIMP-1 in ovarian tumours may not favor tumour growth or metastases explaining the observed lack of association between TIMP-1 and patient prognosis in our study." (PMID 20459644, 2010).
rectal cancer (6 papers, 2006 to 2022). A primary or metastatic malignant neoplasm that affects the rectum. "High TIMP-1 levels indicated poor survival among patients with rectal cancer (HR 1.95, 95% CI 1.17–3.26, P = 0.011), with left-sided tumor (HR 1.95, 95% CI 1.27–3.00, P = 0.002), and with low CRP (HR 1.59, 95% CI 1.05–2.42, P = 0.029)." (PMID 29929486, 2018). "In this view, our intention was to assess the predictive value of serum TIMP-1 levels in cohort of patients with rectal cancer who were treated with preoperative radiochemotherapy." (PMID 23801910, 2013). "The aim of this study was to determine the predictive and prognostic value of TIMP-1 plasma level for local tumour response to preoperative radiochemotherapy and survival in patients with rectal cancer." (PMID 23801910, 2013). "Patients with rectal cancer had statistically significantly higher mean and median TIMP-1 level than healthy blood donors which is in accordance with the results published in other publications." (PMID 22933958, 2011). "TIMP-1 levels in patients with rectal cancer were statistically significantly higher than TIMP-1 levels in healthy blood donors (P<0.0001)." (PMID 22933958, 2011). "Patients with rectal cancer had statistically significant higher TIMP-1 levels in comparison with healthy blood donors (P<0.0001)." (PMID 22933958, 2011). "Patients with rectal cancer had statistically significantly higher mean and median TIMP-1 level than healthy blood donors which is in accordance with the results published in others publications." (PMID 22933958, 2011). "When analysing the association between established clinicopathological parameters and TIMP-1, we found elevated TIMP-1 levels in patients with higher cT-stage and those who died from rectal cancer or had increased CRP before the start of the preoperative treatment." (PMID 23801910, 2013). "The purpose of the study was to analyse whether the levels of the tissue inhibitor of matrix metalloproteinases-1 (TIMP-1) are higher in patients with rectal cancer as compared with healthy blood donors." (PMID 22933958, 2011). "Serum TIMP-1 levels were found to be significantly increased in patients with preoperative CRP>12 mg/L and in those who died from rectal cancer or had cT4 tumours." (PMID 23801910, 2013). "Serum TIMP-1 levels were found to be significantly increased in patients with preoperative CRP>12 mg/L and in those who died from rectal cancer and were marginally increased in patients who had cT4 tumours." (PMID 23801910, 2013). "In rectal cancer, high MMP-9 and high TIMP-1 served as prognostic factors." (PMID 29929486, 2018). "Therefore, we classified colorectal cancer into colon and rectal cancer and examined differences in the expression of MMP-2, MMP-9, TIMP-1, TIMP-2, uPA, uPAR and PAI-1 between colon and rectal cancer." (PMID 16916471, 2006).
schistosomiasis (6 papers, 2011 to 2018). An infectious disease caused by parasitic trematodes of the genus Schistosoma that colonize human blood vessels and release eggs that can cause granulomatous reactions leading to acute (swimmer's itch or acute schistosomiasis syndrome) or chronic disease. "In schistosomiasis, MMP-1 and -2 and TIMP-1 and -2 have been linked to active periovular granulomas in humans, whereas increased levels of MMP-8 and -10, and TIMP-1 and -2 were observed in mice." (PMID 30089120, 2018). "TIMP1 was also elevated in experiments using trophoblast cells co-cultured with plasma from pregnant women with schistosomiasis history or direct stimulation with SEA." (PMID 25965781, 2015). "In vitro, we demonstrated that CXCL9 and CXCL10 inhibited the expression of collagen, TGF-β and TIMP1 of hepatic non-parenchymal cells of mice infected with S. japonicum, while increased the gene expression of MMP9, suggesting that they played an anti-fibrosis role in the liver of schistosomiasis." (PMID 22905138, 2012).
thoracic aortic aneurysm (6 papers, 2015 to 2024). An aneurysm formed in the wall of the proximal portion of the descending aorta proceeding from the arch of the aorta. "There is a differential expression with MMP-9 increased and TIMP-1 and -2 reduced in the most common forms of thoracic aortic aneurysms." (PMID 37175712, 2023).
Turner syndrome (6 papers, 2018 to 2025). Turner syndrome is a chromosomal disorder associated with the complete or partial absence of an X chromosome. "Analysis of individuals with Turner syndrome with varying second sex chromosome karyotypes showed that the combined loss of TIMP1 and the presence of the TIMP3 risk allele significantly increased risk for BAVD." (PMID 34821691, 2021). "TIMP polymorphisms have also been shown to play an important role in the development of BAV aortopathy, with one study particularly showing that deleterious variants of TIMP-3 and hemizygous genotype of TIMP-1 pose an increased risk of developing this condition in patients with Turner syndrome." (PMID 35563383, 2022). "In order for the most significant comorbidities such as BAV to be fully understood in Turner syndrome, more research will need to determine the interplay between genes such as TIMP1 and their epigenetic modifications." (PMID 34821691, 2021). "We propose that the combination of X chromosome TIMP1 hemizygosity and variants of its autosomal paralogue TIMP3, significantly increases the risk of aortopathy in Turner syndrome." (PMID 30281655, 2018). "We propose that hemizygosity for TIMP1 is the X chromosome basis for increased susceptibility for BAV and aortopathy in Turner syndrome." (PMID 30281655, 2018). "The inherent decrease in TIMP1 in Turner syndrome subjects missing a complete second copy of the X chromosome sensitizes those individuals to decreased TIMP3 expression." (PMID 30281655, 2018). "Loss of TIMP3 expression may be compensated for by an increase in TIMP1, which cannot occur in Turner syndrome when there is hemizygosity of TIMP1." (PMID 34821691, 2021). "Attributes of Turner syndrome subjects with 1 or >1 copy of TIMP1." (PMID 30281655, 2018). "Beyond Turner syndrome, the lack of a second copy of TIMP1 in euploid males may also explain the increased risk for BAV/TAD compared to euploid females." (PMID 30281655, 2018). "Interestingly, none of the patients from the study had Turner’s syndrome that confers strong predisposition to development of BAV and is related to homozygosity for TIMP1 gene." (PMID 37632572, 2023).
type 1 diabetes (6 papers, 2014 to 2023). "A cross-sectional study showed associations of plasma levels of MMP9 and TIMP1 with PN in type 1 diabetes." (PMID 35651981, 2022). "Besides these limitations, the current study, with extensive adjustments for potential confounders and mediators, provides additional and consistent information on ECM remodeling by MMPs and TIMP-1 preceding incident CVD and all-cause mortality in a large cohort of patients with type 1 diabetes." (PMID 28446168, 2017). "In view of these considerations, we investigated associations, in type 1 diabetes, between plasma MMP-1, -2, -3, -9 and -10, and TIMP-1 and incident non-fatal and fatal cardiovascular events, as well as all-cause mortality, in a prospective study with more than 12 years of follow-up." (PMID 28446168, 2017). "The aim of the present study was to elucidate the effects of type 1 diabetes on the condylar response during treatment with a functional appliance by analyzing the expression levels of matrix metalloproteinase (MMP)-8, MMP-9 and tissue inhibitor of metalloproteinase-1 (TIMP-1)." (PMID 25289023, 2014).
brain tumor (5 papers, 2016 to 2025). "The protein expression of MMP9, MMP13, TIMP1, TIMP2, and TIMP4 was elevated in all three investigated brain tumor diagnoses." (PMID 38474106, 2024). "In contrast, the tissue inhibitor metalloproteinase-1 (TIMP-1) presented higher expression, which is an important inhibitor of MMP, and plays a crucial role in brain tumor invasion." (PMID 35300350, 2021).
Burkitt lymphoma (5 papers, 2013 to 2023). A rare form of malignant mature B-cell non-Hodgkin lymphoma. "For example, in Burkitt’s lymphoma, the use of doxorubicin treatment can cause the thymus to release IL-6 and tissue inhibitor of metalloproteinase 1 (TIMP1), causing the remaining lymphoma tissue to resist the drug, which leads to the recurrence of lymphoma." (PMID 35668934, 2022). "A previous study has shown that IL-6 and TIMP-1 contribute to the chemoresistant niche promoting survival of tumor cells in a murine model of Burkitt’s lymphoma; however, the direct relationship between TIMP-1 and IL-6 remained unexplored." (PMID 31443242, 2019). "Induction of TIMP-1 expression in an EBV-negative Burkitt's lymphoma cell line results in a biphasic tumor growth in nude mice." (PMID 26556867, 2015). "MMP-independent roles for TIMP-1 in biological processes include anti-apoptotic effects of TIMP-1 in several human cells, such as Burkitt’s lymphoma, breast epithelial cells, and cardiomyocytes." (PMID 23967215, 2013).